NT5C2 (5'-nucleotidase, cytosolic II)
Diseases named in the same sentence as NT5C2 in open-access papers (continued):
Sharing a sentence is not in itself a finding about the gene and the disease.
osteosarcoma (1 paper, 2017). A usually aggressive malignant bone-forming mesenchymal neoplasm, predominantly affecting adolescents and young adults. "Taken together, results revealed that circ-NT5C2 was up-regulated in osteosarcoma tissue compared with adjacent noncancerous tissue, acting as a valuable diagnostic marker for osteosarcoma detection." (PMID 29383123, 2017). "In present study, our team investigates the circRNAs expression profiles in osteosarcoma tissue and determines the tumorous roles of circ-NT5C2 in osteosarcoma tumorigenesis." (PMID 29383123, 2017). "In present study, we found that circ-NT5C2 was up-regulated in osteosarcoma tissue and cells, and function as oncogenic molecular in the tumorigenesis, providing a valuable diagnostic marker and therapeutic target for osteosarcoma detection." (PMID 29383123, 2017). "Functional validation experiments verified that circ-NT5C2 silencing suppressed the proliferation and invasion, and promoted apoptosis of osteosarcoma cells in vitro." (PMID 29383123, 2017). "Furtherly, circ-NT5C2 expression levels were up-regulated in 36.5% (19/52 cases of samples) of osteosarcoma tissue samples, and down-regulated in 63.5% (33/52) of that compared with adjacent non-tumor tissue." (PMID 29383123, 2017). "The aim of this study is to characterize the circRNA expression profiles of osteosarcoma tissue and identify the physiological function of circ-NT5C2, thus providing new insight into the molecular signatures of osteosarcoma tumorigenesis." (PMID 29383123, 2017). "Circ-NT5C2 functions as an oncogenic molecular through targeting miR-448, acting as miRNA ‘sponge’, which provides novel insights for the osteosarcoma carcinogenesis." (PMID 29383123, 2017). "Thus, not limited in the expression profiles screening, we also identified the biological function of one typical representative, suggesting the oncogenic role of circ-NT5C2 in osteosarcoma tumorigenesis." (PMID 29383123, 2017). "Overall, results indicated that circ-NT5C2 silencing could suppress the osteosarcoma cells progression in vivo and in vitro." (PMID 29383123, 2017). "Overall, our study investigates the circRNAs expression profiles and determines the function of circ-NT5C2 in osteosarcoma tumorigenesis, which might serve as a novel therapeutic target of osteosarcoma patients." (PMID 29383123, 2017).
tumor (18 papers, 2015 to 2025). "However, the GG genotype was associated with higher NT5C2 mRNA levels and Ara-C cytotoxicity as well as tumor cell resistance to Ara-C in HapMap samples, which was also associated with Ara-C sensitivity of primary AML leukemic blasts." (PMID 29141648, 2017). "High expression of NT5C2, NT5DC2, and NT5DC3 was closely associated with higher tumor stage and poor overall survival (OS)." (PMID 35047040, 2022). "Our findings showed that NT5C2, NT5DC2, and NT5DC3 expression was associated with higher tumor pathologic stage and poor OS." (PMID 35047040, 2022). "We used three datasets (BRCA_GSE110686, BRCA_GSE114727_10X, and BRCA_GSE114727_inDrop) of the TISCH web tool to interpret NT5C2 and NT5DC2 expression in tumor microenvironment-related immune cells." (PMID 36820551, 2023). "We observed that the expression of NT5C2 (P=0.0055), NT5DC2 (P=0.027), and NT5DC3 (P=0.035) was closely correlated with tumor stage, suggesting that the expression of NT5C2, NT5DC2, and NT5DC3 increased significantly with the progression of HCC." (PMID 35047040, 2022). "Very encouragingly, the first-in-class small molecule NT5C2 inhibitor CRCD2 was efficient against ALL tumor cells both in vitro and in vivo in mice, without detectable adverse effects (besides minimal weight loss)." (PMID 39947478, 2025). "Many studies showed that NT5C2, NT5DC2, and NT5DC3 played an important role in tumor development." (PMID 35047040, 2022). "However, TK2 and NT5C2 were not significantly upregulated in tumor tissues." (PMID 32638267, 2020).
cancer (16 papers, 2011 to 2026). A tumor composed of atypical neoplastic, often pleomorphic cells that invade other tissues. "Two of them also belong to the set of cancer mutated genes, fumarate hydratase (FH) and 5′-nucleotidase, cytosolic II (NT5C2)." (PMID 36880517, 2023). "In a previous paper, we noticed a decrease of cell proliferation and motility, an increase of oxidative metabolism and a strong decrease of the rate of protein synthesis in cancer cell models after silencing NT5C2 to approximately 50%." (PMID 33477638, 2021). "We have a particular interest in the 5′-nucleotidases CD73 (NT5E) and cN-II (NT5C2) in cancer cells." (PMID 34831141, 2021). "Here, we identify the induction of 5′-nucleotidase, cytosolic II (NT5C2) gene expression promotes inosine accumulation and maintains cancer cell survival in the nutrient-poor region." (PMID 37532694, 2023). "The expressions of NT5C2 and NT5DC1/2/3 proteins were closely correlated with the grades of cancer." (PMID 37576396, 2023).
neurological disorders (2 papers, 2015 to 2023). "Fluctuations of cN-II expression and activity have been associated with highly proliferating cells and neurological disorders, and mutations in NT5C2 (the gene encoding cN-II) have been reported to drive pharmacological resistance in hematological tumors." (PMID 25811392, 2015).
psychiatric disorder (2 papers, 2019 to 2026). A disorder characterized by behavioral and/or psychological abnormalities, often accompanied by physical symptoms. "Ultimately, these data demonstrate biological mechanisms associated with NT5C2 that may explain its association with psychiatric disorders." (PMID 31097295, 2019). "To extend our previous work and investigate the relationship between NT5C2 expression and psychiatric disorders, we investigated which cell types express this gene in the adult brain." (PMID 31097295, 2019). "The role of NT5C2 in psychiatric disorders has been previously hypothesized to begin during neurodevelopment, a period underscored by complex processes implicated in major psychiatric disorders, with this risk mechanism persisting in the adult brain." (PMID 31097295, 2019).
hematological cancers (1 paper, 2023). "NT5C2 has been identified as an important therapeutic target in hematological cancers." (PMID 37576396, 2023).
infection (1 paper, 2017). The state of being infected such as from the introduction of a foreign agent such as serum, vaccine, antigenic substance or organism. "Real-time PCR analysis was performed to confirm the microarray results for Stat1, Stat2, Zfp456, Nt5c2, NfκB2 and Samd9l post V3000 and V3034 infections at various time points." (PMID 28446152, 2017). "Genes like B2m, Mst1, Igsf1, Ifitm3 and Nt5c2 were found to be upregulated whereas genes like Fyb, Ilf3, Wnt4 and Socs3 were found to be downregulated in the brain against both V3000 and V3034 infections." (PMID 28446152, 2017). "Real-time PCR analysis was performed to confirm the microarray results for randomly selected genes a) Stat1, b) Stat2, c) Zfp456, Nt5c2 and NfκB2 post V3000 infection and d) Samd9l post V3000 and V3034 infections." (PMID 28446152, 2017).
NT5C2 also shares sentences with these, for which no sentence is quoted: acute myeloid leukemia (4 papers); acute leukemia (3); depression (3); diabetes (2); metabolic disease (2); metabolic syndrome (2); Parkinson disease (2); autism (1); cardiac arrhythmia (1); cataract (1); cervical tumors (1); chronic lymphocytic leukaemia (1); Cognitive impairment (1); colon carcinoma (1); colorectal carcinoma (1); coronary heart disease (1); gynecologic cancers (1); hematological malignancies (1); hepatocellular carcinoma (1); hypertriglyceridemia (1); Intellectual disability (1); ischemic stroke (1); leiomyosarcoma (1); lung adenocarcinoma (1); non-small cell lung carcinoma (1); nonalcoholic fatty liver disease (1); Nystagmus (1); ophthalmoplegia (1); optic atrophy (1); ovarian carcinoma (1).
A further 5 diseases each share a sentence with NT5C2 in 1 paper.